UNC13D (unc-13 homolog D)
Diseases named in the same sentence as UNC13D in open-access papers (continued):
Sharing a sentence is not in itself a finding about the gene and the disease.
Hypogammaglobulinemia (1 paper, 2025). "UNC13D deficiency with hypogammaglobulinemia was associated with a higher frequency of respiratory manifestations, neurological involvement, and an increased mortality rate." (PMID 40901478, 2025). "UNC13D variants in patients with hypogammaglobulinemia were predominantly found in exons 9 and 20, which affect the RAB27α interaction domain, crucial for granule-mediated cytotoxicity." (PMID 40901478, 2025). "Our observations suggest that UNC13D deficiency with hypogammaglobulinemia presents a distinct clinical phenotype compared to other HLH patients." (PMID 40901478, 2025). "Comparison about clinical features between UNC13D deficiency with hypogammaglobulinemia and FHL3 in a systematic review." (PMID 40901478, 2025). "Immunological characteristics in UNC13D deficiency with hypogammaglobulinemia." (PMID 40901478, 2025). "Genetic characteristics in UNC13D deficiency with hypogammaglobulinemia." (PMID 40901478, 2025). "Notably, variants in the UNC13D RAB27α-interaction domain were enriched among patients with hypogammaglobulinemia." (PMID 40901478, 2025). "While the mechanism underlying antibody deficiency in UNC13D deficiency remains unclear, insights can be gleaned from mutations in other vesicle transport-related genes, such as STX11." (PMID 40901478, 2025). "Clinical characteristics in UNC13D deficiency with hypogammaglobulinemia." (PMID 40901478, 2025). "Comparison between UNC13D deficiency with hypogammaglobulinemia and sporadic HLH with hypogammaglobulinemia." (PMID 40901478, 2025).
lung carcinoma (1 paper, 2018). "Whole-genome sequencing of human tumors (TCGA cBioPortal) revealed amplification of Munc13-4 mRNA (UNC13D) in breast, pancreatic, and lung carcinomas in up to 28% of tumors, whereas other members of the Munc13 family showed no consistent up-regulation." (PMID 29930202, 2018).
multiple sclerosis (1 paper, 2013). A progressive autoimmune disorder affecting the central nervous system resulting in demyelination. "In this work, we sequenced UNC13D in 21 ALPS and 20 DALD patients and compared these results with sequences obtained from 61 healthy subjects and 38 multiple sclerosis (MS) patients." (PMID 23840885, 2013).
Sepsis (1 paper, 2025). Sepsis is defined as life-threatening organ dysfunction caused by a dysregulated host response to infection. "HLH is a hyperinflammatory syndrome in which familial (primary) forms arise from biallelic variants in cytotoxic-pathway genes (e.g., PRF1, UNC13D, STX11, STXBP2), and in neonates the presentation may closely mimic sepsis." (PMID 41477640, 2025).
systemic inflammatory response syndrome (1 paper, 2024). SIRS is a serious condition related to systemic inflammation, organ dysfunction, and organ failure. "Another systemic inflammatory response syndrome gene and candidate gene for MIS-C is UNC13D, from which we prioritised a non-synonymous variant, namely p.S347P, annotated as ‘variant of unknown significance’ in both the ACMG classifications and ClinVar annotations." (PMID 39844836, 2024).
immune disorder (8 papers, 2012 to 2025). "The final protein, UNC13D, has a critical role in cytotoxic granule exocytosis and has been linked to severe immune disorders like FHL." (PMID 38188011, 2023).
infection (8 papers, 2017 to 2025). The state of being infected such as from the introduction of a foreign agent such as serum, vaccine, antigenic substance or organism. "Although undiagnosed hypomorphic genetic variants in genes such as PRF1 or UNC13D remain a theoretical predisposition, the patient’s rapid response to therapy strongly supports a predominant, infection-driven secondary etiology." (PMID 41357205, 2025). "During HH6VB infection or reactivation, the virus may trigger the activation of the mutated UNC13D gene in patients, leading to decreased NK and T cell activity, release of inflammatory factors, and activation of phagocytes to induce phagocytosis." (PMID 41394838, 2025).
bacterial infections (1 paper, 2020). "Although these cellular differences in Munc13-4 isoform expression could thus have some clinical impact e.g., with respect to susceptibility to bacterial infections, patients with the UNC13D intronic mutation have nonetheless been reported to present with early onset HLH." (PMID 32582217, 2020).
brain disorder (1 paper, 2024). A disease affecting the brain or part of the brain. "We found 7 variants that were associated with neurodevelopment and brain disorders, of which, 4 variants were found in both patients, namely in genes CTBP2, CDC27, UNC13D and IRF8, and 3 variants found in either of the patients, NDUFAF3, MRPS25, MORC3." (PMID 38638145, 2024).
UNC13D also shares sentences with these, for which no sentence is quoted: cancer (5 papers); Chediak-Higashi syndrome (4); Autoimmunity (3); breast carcinoma (3); Immunodeficiency (3); basophil leukemia (2); Hepatosplenomegaly (2); Cerebral atrophy (1); chronic granulomatous disease (1); dysgammaglobulinemia (1); eczema (1); endometrial adenocarcinomas (1); endometrial cancer (1); Evans syndrome (1); Hemophagocytosis (1); hypertriglyceridemia (1); Hypofibrinogenemia (1); infectious mononucleosis (1); lung diseases (1); Lymphadenopathy (1); metabolic disorders (1); metastatic cancer (1); osteopetrosis (1); partial albinism (1); primary immunodeficiencies (1); respiratory infections (1); Splenomegaly (1); Stroke (1); thalassemia (1); transient ischemic attack (1).
A further 3 diseases each share a sentence with UNC13D in 1 paper.